HIC1 (HIC ZBTB transcriptional repressor 1)
Diseases named in the same sentence as HIC1 in open-access papers (continued):
Sharing a sentence is not in itself a finding about the gene and the disease.
tumor (continued). "Cox regression analysis revealed that HIC1 protein downexpression in tumor tissues was an independent factor on patients’ DFS: patients with HIC1 protein downexpression had worse prognosis (P = 0.024; Hazard ratio, 0.296; 95% CI, 0.102~0.855)." (PMID 26510908, 2015). "All of these genes are known to be involved in different aspects of breast carcinogenesis, which includes tumor suppression, HIC1, CDH1, CDH13, CDKN2, DNA repair, MGMT, apoptosis, PYCARD, TNFRSF10C, and cell cycle regulation, CCNA1." (PMID 25403427, 2014). "Endogenously, the HIC1 (Hypermethylated in cancer 1) gene, a tumor suppressor, forms complex with STAT3 protein through direct interaction between the C-terminal domain of HIC1 and the DNA binding domain of STAT3." (PMID 24743778, 2014). "In the Egr2 subnetwork, Egr2 was found to participate in feedforward loops involving the tumor suppressor Hic1 and the miRNAs let-7a and let-7f." (PMID 23387820, 2013). "HIC1 is a candidate tumor suppressor located at 17p13.3, a region frequently found to be hypermethylated or deleted in many types of prevalent human tumors." (PMID 22140553, 2011). "HIC-1 is a newly discovered tumor suppressor and transcriptional repressor which is located at 17p13.3, a region which frequently undergoes allelic loss in human cancers." (PMID 20546602, 2010). "Candidate genes within this region are HIC-1, a potential tumour-suppressor gene, and DPH2L, a gene that has been cloned from the ovarian critical region." (PMID 9374372, 1997). "In PCa, loss of the HIC1 gene increases tumor-cell secretion of TGF-β, promotes monocyte polarization toward M2 macrophages, and converts NFs into CAFs, establishing a cyclical interaction among tumor cells, CAFs, and M2 macrophages." (PMID 41514658, 2025). "HIC1 hypermethylation reduces its tumor expression, significantly upregulating SIRT1." (PMID 41208649, 2025). "HIC1 transforms mesenchymal stem cells (MSCs) into tumor stem cells." (PMID 39267141, 2024). "Furthermore, LCN2 is identified as a direct target gene of Hypermethylated in Cancer 1 (HIC1), a tumor suppressor specifically active in TNBC." (PMID 39188682, 2024). "In the current work, we looked at HIC1's potential function in this tumor type." (PMID 38646326, 2024). "Moreover, TISIDB online database was utilized to explore the effects of HIC1 on mediating tumor-infiltrating lymphocytes, the expression of MHC genes, immunoinhibitory/immunostimulator genes, chemokines, and chemokines receptors during cancer progression." (PMID 37388742, 2023). "Therefore, we perform a pan-cancer analysis to thoroughly explore the clinical significance of HIC1 as well as its critical roles in tumor immune microenvironment and immunotherapy." (PMID 37388742, 2023). "Furthermore, the potential functions of HIC1 in mediating the tumor immune microenvironment and predicting the immunotherapeutic efficacy and drug sensitivity were further investigated." (PMID 37388742, 2023). "To further reveal the role of HIC1 in the tumor immune microenvironment, we first analyzed the relationship between HIC1 expression and immune and stromal scores by the ESTIMATE algorithm, which presented a positive correlation in multiple cancers, such as BLCA, CHOL, and COAD." (PMID 37388742, 2023). "Therefore, future studies are required to investigate the biological functions of HIC1 in tumor immune microenvironment." (PMID 37388742, 2023). "HIC1 was detected in all of the examined tumor tissue samples." (PMID 37388742, 2023).
tumor (continued). "HIC ZBTB transcriptional repressor 1 (HIC1) usually plays a suppressive role in tumor progression." (PMID 36468944, 2023). "To date, little research has been conducted to investigate the role of HIC1 in mediating immune cells in tumor immune microenvironment, which may be a novel direction for exploring the biological functions in oncology." (PMID 37388742, 2023). "As HIC1 is usually hypermethylated or deleted in several types of human tumors and promotes tumor progression, it is now known as a tumor growth regulator and tumor repressor." (PMID 35853880, 2022). "Notably, the CRC members identified include the retinoic acid receptor homologs RARA, RARB and the tumour suppressors HIC1 and SMAD3." (PMID 36147741, 2022). "In tumor tissues, HIC1 expression in stages III–IV was lower than that in stages I–II." (PMID 35853880, 2022). "We speculate the opposite action of HIC1 in affecting tumor initiation and patient outcome may due to the context-specific manner by HIC1 in regulating biological process through different mechanisms." (PMID 35071242, 2021). "Previous evidence suggests that HIC1 hypermethylation may increase along with tumor progression and the level of hypermethylated HIC1 may correspond to tumor aggressiveness and poor prognosis." (PMID 34642302, 2021). "HIC1 (Hypermethylated in Cancer1) is a tumor suppressor gene inactivated by epigenetic silence." (PMID 35095892, 2021). "Moreover, the expression of sirtuin 1 (SIRT1), a deacetylase in tumor cells was upregulated by FBXW11 via regulating HIC1 expression." (PMID 34642302, 2021). "HIC1 is a transcriptional suppressor that is widely regarded as a tumor suppressor gene." (PMID 31795965, 2019). "Lastly, we found that miR-128 accelerated tumor growth in xenograft mice by inhibiting HIC1." (PMID 31680974, 2019). "HIC-1 plays a important role in the physiological regulation of multidrug resistance through the IL-6/STAT3 signal pathway, and has been implicated in the other various tumor." (PMID 30202238, 2018). "In addition, we show for the first time that the tumor suppressor HIC1 is able to promote Tat-dependent HIV-1 transcriptional silencing in microglial cells." (PMID 27725726, 2016). "HIC1 expression was closely correlated with patient age and tumor progression." (PMID 27793057, 2016). "Notably, HIC1 is a tumor suppressor through inhibiting the transcription of IL-6 by sequence-specific binding on its promoter." (PMID 27107418, 2016). "Interestingly, SIRT1 interacts with HIC1, a tumor suppressor and transcriptional repressor that is epigenetically inactivated but not mutated in human cancers." (PMID 25486244, 2014). "In addition, Pokemon was proven to be a type of proto-oncogene, whereas the BTB/POZ protein HIC1 is candidate tumor suppressor in a variety of human tumors." (PMID 19508730, 2009). "In addition, Hypermethylated in cancer 1 protein (Hic-1) has been reported to be underexpressed in tumour cells due to hypermethylation and in mice, heterozygous disruption of the gene has been shown to induce tumours." (PMID 16405732, 2006).
tumor (continued). "Moreover, HIC1 synergized with PD‐L1 to suppress tumorigenesis in 615‐line mice models, indicating that elevated HIC1 expression may render tumor cells more responsive to PD‐L1 therapy." (PMID 40279559, 2025). "HIC1, a tumor suppressor gene, is epigenetically silenced in a variety of tumors, and deleting HIC1 might contribute to premalignant transformation in the early stages of tumor formation." (PMID 33772032, 2021). "The results indicate that HIC1 may play a tumor suppressor role in NSCLC progression." (PMID 27107418, 2016). "Finally, to further explore whether HIC1 is involved in inhibiting tumor metastasis in vivo, we transplanted these luciferase-tagged A549 cells into nude balb/c mice by tail vein injection." (PMID 27107418, 2016). "Our data suggested that HIC1 might be a novel candidate suppressor of tumor progression in ESCC." (PMID 26510908, 2015). "Therefore, HIC-1 is a potential target for gene therapy in gastric cancer, and saRNAs could present a novel therapeutic option for upregulating tumor suppressor genes." (PMID 24489730, 2014). "In this study, we evaluated the expression levels of HIC1, AR, IRS2, and EMT‐related proteins, as well as the activation status of the PI3K/AKT pathway in PCa mouse tumor tissue using RT‐qPCR and Western blot experiments." (PMID 41050263, 2025). "Subsequently, our findings discovered that HIC1 facilitated cell pyroptosis by transcriptionally activating the downstream target GSDMD, leading to an increase in tumor‐infiltrating CD8+ T cells." (PMID 40279559, 2025). "In conclusion, our study refines concepts of p‐EMT and tumor cell invasion in HNSCC and identifies PDPN and HIC1 as potential therapeutic targets for future development." (PMID 40736379, 2025). "Besides, to investigate whether HIC1 expression could serve as an independent prognostic factor for GC, we performed a univariate and multivariate Cox regression analysis adjusting for other clinical variables such as age, gender, and tumor size." (PMID 40279559, 2025). "To further investigate the impact of HIC1/AR/IRS2 on the proliferation and metastasis of PCa cells, we conducted immunohistochemical analysis on PCa xenograft tumor slices." (PMID 41050263, 2025). "However, the roles of HIC1 are inconsistent and controversial among several cancers, there are no pan-cancer analysis of HIC1 and the associations of HIC1 with tumor immune microenvironment and the immunotherapeutic efficacy are still largely unknown." (PMID 37388742, 2023). "The most investigated genes were RASSF1A, BRCA1, OPCML, APC, HIC1, and HOXA9, all being tumor-suppressor genes." (PMID 36788585, 2023). "GDF11 is a tumor suppressor, Class II genes are mainly tumor suppressor, including GDF11, TRPV1 and HIC1." (PMID 36741321, 2023). "Among these overlapping genes, the HIC1 was significantly upregulated in ZBTB7A knockdown cells, and its well-known tumor suppressor gene plays a critical role in various cancers." (PMID 35501800, 2022). "In tumor tissue, IRS of epithelial HIC1 staining indicated that HIC1 expression was lower than that in normal tissue." (PMID 35853880, 2022). "The methylation level in the methylated EOC tumor samples ranged from 4 to 97% for HOXA9; 7–89% for HIC1; 4–97% for SOX1; 4–95% for DAPK1; 5–97% for SFRP1; 6–99% for SPARC and 4–98% for RASSF1A gene, respectively." (PMID 34778370, 2021). "The down-regulation of SIRT1 leads to tumorigenesis and up-regulation of SIRT1 inhibits the activity of several oncogenes such as HIC1 and DBC1 resulting in cell proliferation, apoptosis, and tumor suppression." (PMID 33630973, 2021). "The results revealed that the mRNA expression levels of DLX4, FBN1, HIC1, HOXB9, ONECUT2, and SIX1 were significantly different between tumor samples and normal tissues, which were consistent with the results from TCGA." (PMID 35095892, 2021). "FBN1, HIC1, and SFRP4 were lower in the tumor than normal tissues; the expressions of other ERGs were the opposite." (PMID 35095892, 2021).
tumor (continued). "The promoter methylation levels of selected candidate genes (RASSF1A, DAPK1, SOX1, HOXA9, HIC1, SPARC, and SFRP1) were quantitatively evaluated by MethyLight in tumor DNA samples of patients with EOC." (PMID 34778370, 2021). "Among these ten genes, the expression levels of SETD1B, ACSF2, MUC1, KLHL24, PML, MT1G, and GPT2 were higher in tumor tissues than those in normal tissues, while HIC1, AKR1C1, and LOC390705 were lower expressed in tumor tissues." (PMID 35071242, 2021). "Thus, HIC1 is only weakly expressed in normal human prostate epithelial cells, which are the final target of the transformation process, but is expressed in stromal cells which play a crucial role in tumor initiation and progression through cross-talk with epithelial cells." (PMID 33227080, 2020). "HIC1 is expressed in stromal myofibroblasts and regulates CXCL12/SDF1 expression, thereby highlighting a complex interplay mediating the tumor promoting activity of the tumor microenvironment." (PMID 33227080, 2020). "Pathway analysis showed activation of the transforming growth factor-β pathway in YSTs, which is associated with the overexpression of GATA6 and FOXA2 and the hypermethylation of tumor-suppressor genes (e.g., RASSF1, RUNX3, HIC1, or APC)." (PMID 32999426, 2020). "Functional studies established that ectopic re-expression of HIC1 in ESCC cells inhibited cell proliferation, clonogenicity, cell motility, tumor formation and epithelial-mesenchymal transition (EMT)." (PMID 26510908, 2015). "Statistical analysis revealed 3 genes (HIC1, GSTP1, and RASSF1) capable of significantly predicting tumor recurrence." (PMID 24252461, 2013). "There are over 40 human BTB-ZF family members, many of which are implicated in both haematopoietic and epithelial cancers, where they act as oncogenes (e.g. BCL6, ZBTB7) or tumour suppressors (e.g. PLZF, HIC1) [reviewed in 38]." (PMID 23874226, 2013). "In total, increased HIC1 and SLIT2 promoter methylation and decreased expression were observed in 70.0% and 51.7% of the tumor samples, respectively." (PMID 22140553, 2011). "Tumour-related methylated forms of three genes (RARβ2, RASSF1A and HIC-1) were much more frequently evaluated in the cell-surface-bound cirDNA compared with cell-free cirDNA in tumour-bearing patients." (PMID 16641902, 2006). "It is worth noting that overexpression of HIC1 resulted in a higher tumor inhibition rate of ≈80% in C57BL/6J mice, however, it only trigged a tumor inhibition rate of ≈60% in BALB/C nude mice, suggesting the tumor suppression effect of HIC1 was partially reliant on an efficient immune system." (PMID 40279559, 2025). "The results revealed that the HIC1 overexpression group led to a marked reduction in tumor volumes and weights compared with the negative control group, while the DMF co‐treated group experienced a noticeable increase." (PMID 40279559, 2025). "Furthermore, the reduction in tumor size can be attributed to the enhancement of CD8+ T cells, partially facilitated by the upregulation of HIC1 expression." (PMID 40279559, 2025). "PHF20L1 directly inhibits a series of tumour suppressor factors, including Forkhead Box Protein K2 (FOXK2) and Hypermethylated in Cancer 1 (HIC1), through its synergistic action with the PRC2 and NuRD complexes, thereby driving glycolysis and promoting tumour occurrence." (PMID 40723918, 2025).
tumor (continued). "While the ZEB family of transcription factors has a clear role in p‐EMT, invasion, and colony formation, the role of HIC1 (hypermethylated in cancer‐1), a member of the POZ family of zinc‐finger transcription factors and originally identified as a putative tumor suppressor, is less clear." (PMID 40736379, 2025). "Secondly, the specific mechanisms by which HIC1 regulates the tumor immune microenvironment remain largely unclear and have not been illustrated in experiments." (PMID 37388742, 2023). "Notably, we confirmed that HIC1 suppresses the epithelium secretion of TGF-β, which is an important functional protein in tumor development and malignancy." (PMID 35853880, 2022). "Furthermore, the quantitative evaluation of gene promoter methylation through MethyLight assay was confirmed and validated by clonal bisulfite sequencing of selected tumor tissue and normal DNA samples for HOXA9, HIC1, and SOX1 gene." (PMID 34778370, 2021). "We further stained tumor samples with FBXW11, SIRT1, HIC1, and a proliferation marker, Ki-67." (PMID 34642302, 2021). "Furthermore, 19 CDC73 alterations were observed in 18 (53%) PC samples —including four samples exhibiting tumor invasion into the adjacent tissue and three lesions—followed by alterations in EZH2 (n = 2, 6%) and HIC1 (n = 2, 6%)." (PMID 33778063, 2021). "As a whole, these experiments demonstrated that HIC1 is not detectable by immunohistochemistry in normal or transformed prostate epithelial cells but is expressed in normal and tumor stroma." (PMID 33227080, 2020). "Hic1, Inpp5k, and Myo1c showed reduced expression in tumor samples irrespective of the presence or absence of physical deletion in the candidate region, suggesting the potential involvement of alternative gene silencing regulatory mechanism(s)." (PMID 26170120, 2015). "A study on the role of CpG island methylation of HIC1 in RCC using bisulfite conversion and pyrosequencing in 98 tumor and 70 normal adjacent tissue specimens identified HIC1 hypermethylation in tumors as an independent predictor of reduced recurrence-free survival." (PMID 26198328, 2015). "Although hazard ratio is not obvious, we also found in the present study that HIC1 downexpression is one of the affecting factors on tumor progression by multivariate analysis (P = 0.024)." (PMID 26510908, 2015). "We identify a novel pathway that linking HIC1 downregulation to EphA2-inducing EMT in ESCC cells and may shed light on the development of novel anti-tumor therapeutics." (PMID 26510908, 2015). "It interacts with tumor suppressors such as RB and its family members, LKB1 and HIC1, and this interaction may have a role in the repression of E2F-responsive genes and growth suppression." (PMID 23533649, 2013). "HIC1 (hypermethylated in cancer) is a tumor suppressor gene unique in the sense that it has never been found mutated but is found silenced by hypermethylation." (PMID 16248899, 2005). "In contrast, methylation of HIC-1 promoter region, which was examined here, is not tumour specific." (PMID 16641902, 2006).